GALNS (galactosamine (N-acetyl)-6-sulfatase)
Description:
Lysosomal enzyme that hydrolyzes sulfate groups from glycosaminoglycans (GAGs), keratan sulfate (KS) and chondroitin-6-sulfate (C6S).
Synonyms: GalN6S; GAS; GALNAC6S; MPS4A
Tractability: Antibody: its Gene Ontology location is reachable by antibodies, with high confidence; UniProt predicts a signal peptide or a membrane-spanning region. PROTAC: its protein half-life has been measured.
Target class: Enzyme; Hydrolase
Gene: Protein-coding gene on chromosome 16 (88,813,733 to 88,856,970, reverse strand). Ensembl gene ENSG00000141012.
Subcellular location: Lysosome
Subcellular location (Human Protein Atlas): Cytosol
Pathways (Reactome):
Disease: MPS IV - Morquio syndrome A
Immune System: Neutrophil degranulation
Metabolism: Keratan sulfate degradation
Gene Ontology:
Molecular function: N-acetylgalactosamine-6-sulfatase activity; sulfuric ester hydrolase activity; arylsulfatase activity; N-acetylgalactosamine-4-sulfatase activity
Biological process: chondroitin sulfate proteoglycan catabolic process
Cellular component: extracellular exosome; lysosome; azurophil granule lumen; extracellular region; lysosomal lumen
Genetic constraint (gnomAD): Loss-of-function variants: 66 observed, 64.74 expected, observed/expected ratio (o/e) 1.02, 90% interval 0.83 to 1.25. The synonymous counts are far from expectation, so gnomAD's model fits this gene poorly and the ratio says little. Missense variants: 776 observed, 673.09 expected, observed/expected ratio (o/e) 1.15, 90% interval 1.09 to 1.22. Synonymous variants: 346 observed, 277.53 expected, observed/expected ratio (o/e) 1.25, 90% interval 1.14 to 1.36.
Gene-disease validity (ClinGen):
ClinGen rates the evidence that GALNS causes each of these diseases.
mucopolysaccharidosis type 4A (autosomal recessive): Definitive. A rare autosomal recessive lysosomal storage disease caused by deficiency of the enzyme galactosamine-6-sulfatase.
Homologues: Orthologues: dog GALNS (86% identical), macaque GALNS (85% identical), mouse Galns (84% identical), guinea pig GALNS (83% identical), chimpanzee GALNS (82% identical), rat Galns (76% identical), pig GALNS (72% identical), tropical clawed frog galns (71% identical), zebrafish galns (67% identical), rabbit GALNS (53% identical), Drosophila melanogaster CG7402 (27% identical), Drosophila melanogaster CG32191 (25% identical), and 3 more. Paralogues in human: ARSA (35% identical), STS (34% identical), ARSD (34% identical), ARSG (34% identical), ARSL (34% identical), ARSH (32% identical), ARSF (32% identical), ARSI (27% identical), ARSB (25% identical), ARSJ (25% identical), SGSH (25% identical), IDS (23% identical), and 4 more.
Diseases named in the same sentence as GALNS in open-access papers:
GALNS is named in the same sentence as 53 diseases in open-access papers, as found by Europe PMC text mining. Sharing a sentence is not in itself a finding about the gene and the disease. The quoted sentences say what the papers report.
Morquio A syndrome (69 papers, 2010 to 2025). "Mucopolysaccharidosis type IVA (MPS IVA or Morquio A syndrome) is an autosomal recessive lysosomal disorder caused by mutations in the N-acetyl-galactosamine-6-sulfate sulfatase (GALNS) gene, leading to a deficiency of the GALNS enzyme." (PMID 41296404, 2025). "Mucopolysaccharidosis (MPS) IVA (Morquio A syndrome) is an autosomal recessive lysosomal storage disorder caused by a mutation affecting the enzyme N-acetylgalactosamine-6-sulfatase (EC 3.1.6.4, GALNS)." (PMID 39897469, 2025). "Morquio A syndrome is a lysosomal disorder caused by the deficiency of the lysosomal enzyme N-acetylgalactosamine 6-sulfatase (GALNS, EC 3.1.6.4)." (PMID 40430394, 2025). "Among these, MPS IVA (Morquio A syndrome) is characterized by a deficiency in the N-acetylgalactosamine-6-sulfate sulfatase (GALNS) enzyme, which leads to the accumulation of keratan sulfate (KS) and chondroitin-6-sulfate (C6S)." (PMID 40430081, 2025). "Biallelic pathogenic variants in the GALNS gene lead to Mucopolysaccharidosis Type IVA (MPS IVA), a rare lysosomal storage disorder." (PMID 40382551, 2025). "MPS IVa (Morquio A syndrome) is caused by pathogenic mutations in GALNS and is associated with deficiency of the enzyme N-acetylgalactosamine-6-sulfatase (GALNS), resulting in pathological accumulation of keratan sulfate and chondroitin-6-sulfate." (PMID 39020431, 2024). "In patients with mucopolysaccharidosis IVA, a deficiency in the N-acetylgalactosamine-6-sulfate sulfatase (GALNS) enzyme results in an accumulation of GAGs, keratan sulfate, and chondroitin-6-sulfate in the lysosomes of all tissues." (PMID 37111652, 2023). "The results of the GenoDENT test showed variants in the GALNS gene responsible for mucopolysaccharidosis type 4A." (PMID 37228816, 2023). "Mucopolysaccharidosis type IVA (MPS IVA; Morquio syndrome A) is an autosomal recessive lysosomal storage disease caused by variants in the galactosamine-6-sulfate sulfatase gene (GALNS), located on chromosome 16q24.3." (PMID 37228816, 2023). "Morquio A disease is a genetic disorder resulting in N-acetylgalactosamine-6-sulfate sulfatase (GALNS) deficiency, and patients are currently treated with enzyme replacement therapy via weekly intravenous enzyme infusions." (PMID 37513843, 2023). "Mucopolysaccharidosis IVA (MPS IVA) is a rare disorder caused by mutations in the N-acetylgalactosamine-6-sulfate-sulfatase (GALNS) encoding gene." (PMID 38003337, 2023). "MPS IVA, also known as Morquio A syndrome, is caused by pathogenic variants in the gene encoding the enzyme N-acetylgalactosamine-6-sulfate sulfatase (GALNS)." (PMID 35331284, 2022). "MPS IVA, also known as Morquio A syndrome, arises from loss of activity of the enzyme N-acetyl-galactosamine-6-sulfatase (GALNS), which breaks down the GAGs keratan sulfate (KS) and chondroitin sulfate (CS)." (PMID 35236367, 2022). "Mucopolysaccharidosis type IVA (MPS IVA, OMIM #253000) or Morquio A syndrome is an autosomal recessive disease caused by mutations in the GALNS gene." (PMID 34200496, 2021). "Mucopolysaccharidosis IVA (MPS IVA), or Morquio A syndrome, is an ultra-rare, multi-systemic disorder caused by a deficiency of the enzyme N-acetylgalactosamine-6-sulfatase (GALNS; EC 3.1.6.4)." (PMID 33478511, 2021). "Mucopolysaccharidosis IVA (MPS IVA, Morquio A syndrome) is an autosomal recessive disorder characterized by the deficiency of the lysosomal enzyme N-acetylgalactosamine-6-sulfate sulfatase (GALNS)." (PMID 33957983, 2021). "Morquio A syndrome (Mucopolysaccharidosis (MPS) IVA (MPS IVA)) is a lysosomal storage disease caused by the deficiency of N-acetylgalactosamine-6-sulfate sulfatase (GALNS)." (PMID 32365519, 2020). "Mucopolysaccharidosis type IVA (MPS IVA) is a lysosomal storage disease caused by mutations in the N-acetylgalactosamine-6-sulfatase (GALNS) gene." (PMID 33379360, 2020).
Morquio A syndrome (continued). "Mucopolysaccharidosis type IVA (MPS IVA) is a rare genetic disease caused by mutations in the GALNS gene and is inherited in an autosomal recessive manner." (PMID 30797135, 2019). "Mucopolysaccharidosis IVA (MPS IVA) is an autosomal recessive lysosomal storage disease due to N-acetylgalactosamine-6-sulfatase (GALNS) deficiency." (PMID 31200731, 2019). "MPS IVA or Morquio A syndrome (253000) is an autosomal recessive MPS disorder caused by deficiency of the N-acetylgalactosamine-6-sulfatase (GALNS) enzyme (EC 3.1.6.4), which impairs lysosomal degradation of keratan sulphate and chondroitin-6-sulphate." (PMID 31196221, 2019). "Mucopolysaccharidosis IVA (Morquio A) is a rare inherited metabolic disease caused by deficiency of the lysosomal enzyme N-acetylgalatosamine-6-sulfate-sulfatase (GALNS)." (PMID 31614479, 2019). "In this Morquio A syndrome, serum KS increases due to deficiency of N-acetylgalactosamine-6-sulfate sulfatase (GALNS), which is required to degrade KS." (PMID 26448753, 2015). "Mucopolysaccharidosis (MPS) IVA (OMIM #253000), also known as Morquio A syndrome, is an autosomal recessive lysosomal storage disorder caused by deficient activity of N-acetylgalactosamine-6-sulfatase (GALNS)." (PMID 22176730, 2011). "Mucopolysaccharidosis IVA (MPS IVA; Morquio A syndrome) is a lysosomal storage disorder caused by deficiency of N-acetylgalactosamine-6-sulfatase (GALNS), an enzyme that degrades keratan sulfate (KS)." (PMID 20808938, 2010). "Mucopolysaccharidosis IVA, or Morquio A syndrome, is caused by defects in the enzyme N-acetylgalactosamine-6-sulfate sulfatase (GALNS), leading to abnormal accumulation of keratansulfate (KS) and chondroitin-6-sulfate (C6S) in multiple tissues, mainly bone, cartilage, heart valves, and cornea." (PMID 35538504, 2022). "Mucopolysaccharidosis-IVA (Morquio A disease) is a lysosomal disorder in which the abnormal accumulation of keratan sulfate and chondroitin-6-sulfate is consequent to mutations in the galactosamine-6-sulfatase (GALNS) gene." (PMID 30305043, 2018). "Mucopolysaccharidosis type IVA, also known as Morquio (Morquio-Brailsford) syndrome results from accumulation of keratan sulfate (KS) and chondroitin-6-sulfate (C6S), whereas the primary cause is mutations in the gene encoding galactosamine (N-acetyl)-6-sulfatase (GALNS)." (PMID 30927141, 2019). "Mucopolysaccharidosis type IVA (MPS IVA; Morquio A syndrome) is an autosomal recessive lysosomal storage disorder caused by deficiency of N-acetylgalactosamine-6-sulfatase (GALNS), an enzyme essential for the degradation of keratan sulfate and chondroitin-6-sulfate." (PMID 41399535, 2025). "Mucopolysaccharidosis Type IVA (MPS IVA, OMIM 253000) is an inherited lysosomal storage disorder caused by a deficiency of the N- acetylgalactosamine-6-sulfate sulfatase enzyme (GALNS)." (PMID 40382551, 2025). "Mucopolysaccharidosis IVA (MPS IVA, Morquio A syndrome) is a rare autosomal recessive lysosomal storage disorder caused by mutations in the N‐acetylgalactosamine‐6‐sulfatase (GALNS) gene." (PMID 34387910, 2021). "Mucopolysaccharidosis type IVA (MPSIVA) or Morquio A disease, a lysosomal storage disorder, is caused by N-acetylgalactosamine-6-sulfate sulfatase (GALNS) deficiency, resulting in keratan sulfate (KS) and chondroitin-6-sulfate accumulation." (PMID 34504088, 2021). "Mucopolysaccharidosis IVA (MPS IVA, also called Morquio A syndrome) is caused by a deficiency of N‐acetylglucosamine‐6‐sulfate sulfatase (GALNS) and results in skeletal dysplasia symptoms such as short stature and abnormal gait." (PMID 34623762, 2021). "Morquio A syndrome, also called mucopolysaccharidosis IVA (MPS IVA), is an ultra-rare, genetically transmitted lysosomal storage disorder caused by a deficiency of the N-acetylgalactosamine-6-sulfatase (GALNS) enzyme." (PMID 32993725, 2020).
Morquio A syndrome (continued). "Morquio A syndrome, or mucopolysaccharidosis type IVA (MPS IVA, OMIM #253000), is an autosomal recessive disease caused by mutations in the GALNS gene." (PMID 33379360, 2020). "Mucopolysaccharidosis (MPS) IVA or Morquio A syndrome is an autosomal recessive lysosomal storage disorder (LSD) caused by deficiency of the N-acetylgalactosamine-6-sulfatase (GALNS) enzyme, which impairs lysosomal degradation of keratan sulphate and chondroitin-6-sulphate." (PMID 31196221, 2019). "Mucopolysaccharidosis type IVA (MPS IVA, also called Morquio syndrome type A) is a rare autosomal recessive disorder caused by mutations in the GALNS gene, which encodes N-acetylgalactosamine-6-sulfatase (EC 3.1.6.4)." (PMID 30797135, 2019). "Morquio A syndrome, or mucopolysaccharidosis type IVA (MPS IVA), is a lysosomal storage disease due to mutations in the N-acetylgalactosamine-6-sulfatase (GALNS) gene." (PMID 31540344, 2019). "Morquio A syndrome, mucopolysaccharidosis (MPS) IV A, is an autosomal recessive lysosomal storage disorder caused by N-acetylgalactosamine-6-sulfatase (GALNS) activity deficiency." (PMID 29275451, 2018). "Among the different types of MPS diseases, MPS IVA (Morquio A syndrome; OMIM 253000) is a relatively rare autosomal recessive inherited disorder caused by N-acetylgalactosamine-6-sulfatase (GALNS) deficiency." (PMID 30157891, 2018). "Morquio A syndrome, or mucopolysaccharidosis (MPS) IVa, is an ultra-rare, inherited lysosomal storage disorder caused by a deficiency in the enzyme N-acetylgalactosamine-6-sulfatase (GALNS)." (PMID 24602160, 2014). "Morquio A syndrome, or mucopolysaccharidosis IVA (MPS IVA), is an autosomal recessive lysosomal storage disorder caused by defective activity of N-acetyl-galactosamine-6-sulfatase (GALNS), an enzyme that catabolizes the glycosaminoglycans keratan sulfate and chondroitin-6-sulfate." (PMID 25001525, 2014). "The diagnosis of MPS type IVA was confirmed by molecular analysis of the GALNS gene, which detected a compound heterozygosity of genotype p.H154Q/p.G290S (base change c.518C>A/c.924G>A), consistent with the diagnosis of Morquio A syndrome." (PMID 24348578, 2013). "Mucopolysaccharidosis (MPS) IVA (Morquio A syndrome, OMIM #253000) is an autosomal recessive lysosomal storage disorder caused by a mutation in GALNS, which encodes the enzyme N-acetylgalactosamine-6-sulfatase (EC 3.1.6.4, GALNS)." (PMID 39897469, 2025). "Mucopolysaccharidosis IVA (MPS IVA, Morquio A syndrome) is a rare lysosomal storage disorder caused by mutations in the GALNS gene, resulting in N-acetylgalactosamine-6-sulfatase (GALNS) deficiency and accumulation of keratan sulfate and chondroitin-6-sulfate." (PMID 41088244, 2025). "Mucopolysaccharidosis type IVA (MPS IVA; Morquio Syndrome [OMIM #253000]) is a rare, incurable, autosomal recessive lysosomal storage disorder (LSD) that is caused by a deficiency of the enzyme N-acetyl-galactosamine-6-sulfatase - GALNS." (PMID 39039523, 2024). "Mucopolysaccharidosis type IVA (MPS IVA), also known as Morquio A syndrome, is a rare lysosomal storage disease characterized by autosomal recessive inheritance of mutations in the N-acetylgalactosamine-6-sulfatase (GALNS) gene." (PMID 39541578, 2024). "Mucopolysaccharidosis IVA (MPS IVA; Morquio A syndrome) is caused by a deficiency of the N-acetylgalactosamine-6-sulfate-sulfatase (GALNS) enzyme, leading to the accumulation of glycosaminoglycans (GAG), keratan sulfate (KS) and chondroitin-6-sulfate (C6S), mainly in cartilage and bone." (PMID 37373036, 2023). "A decrease in two lysosomal enzymes, N-acetylgalactosamine-6-sulfatase (GALNS) and iduronate-2-sulfatase (IDS) could cause diseases of mucopolysaccharidoses: Morquio A syndrome and Hunter disease, respectively." (PMID 36080188, 2022).
Morquio A syndrome (continued). "Mucopolysaccharidosis type IVA (MPS IVA or Morquio A), a lysosomal storage disease with an autosomal recessive inherited pattern, is induced by GALNS gene mutations causing deficiency in N-acetylgalactosamine-6-sulfatase activity (GALNS; EC 3.1.6.4)." (PMID 36013287, 2022). "MPS is classified into different subtypes according to the lack of different enzymes, and MPS IVA (also called Morquio A syndrome) is caused by the deficiency of N-acetylgalactosamine-6-sulfate sulfatase (GALNS)." (PMID 33407246, 2021). "Mucopolysaccharidosis type IVA (MPSIVA; Morquio A disease: OMIM #253000) is an autosomal recessive Lysosomal Storage Disorder (LSD) caused by the deficiency of N-acetylgalactosamine-6-sulfate sulfatase (GALNS, EC 3.1.6.4)." (PMID 34504088, 2021). "Mucopolysaccharidosis type IVA (MPS IVA) is an inborn error of glycosaminoglycan (GAG) catabolism characterized by a deficiency of the lysosomal enzyme, N‐acetylgalactosamine 6‐sulphatase (GALNS)." (PMID 32905071, 2020). "Mucopolysaccharidosis type IVA (Morquio syndrome A, OMIM MPS IVA 253000) is an autosomal recessive disorder caused by the deficiency of the lysosomal enzyme, N-acetylgalactosamine-6-sulfatase (GALNS; 612222)." (PMID 32093402, 2020). "Mucopolysaccharidosis type IVA (MPS IVA, also called Morquio Syndrome type A; OMIM 253000) is an autosomal recessive disorder caused by a deficiency of the lysosomal enzyme N-acetylgalactosamine-6-sulfate sulfatase (GALNS)." (PMID 31450640, 2019). "Mucopolysaccharidosis type IVA, also known as Morquio A or MPS IV A, is an autosomal recessive disease caused by the deficiency of the lysosomal enzyme N-acetylgalactosamine-6-sulfate sulfatase (GALNS)." (PMID 28904929, 2017). "Mucopolysaccharidosis IVA (MPS IVA) or Morquio A syndrome (ORPHA: 309297, OMIM: 253000) is a rare, autosomal recessive lysosomal storage disorder (LSD) caused by mutations in the GALNS gene, resulting in the deficiency of N-acetyl-galactosamine-6-sulfate sulfatase (GALNS) enzyme." (PMID 40724866, 2025). "Enzyme replacement therapy for MPS IVA using recombinant human GALNS, or elosulfase alfa, was approved by FDA and EMA in 2014, for children and adults with Morquio A syndrome." (PMID 35331284, 2022). "Mucopolysaccharidosis IVA (MPS IVA or Morquio A syndrome; MIM# 253000) is an autosomal recessive lysosomal storage disorder caused by mutations in the GALNS gene, which encodes for the enzyme N‐acetylgalactosamine‐6‐sulfatase (GALNS; EC 3.1.6.4)." (PMID 34387910, 2021). "Mucopolysaccharidosis type IVA (MPS 4A), also known as Morquio (Morquio-Brailsford) syndrome results from the accumulation of keratan sulfate (KS) and chondroitin-6-sulfate (C6S), whereas the primary cause is mutations in the gene encoding N-acetyl-galactosamine-6-sulfatase (GALNS)." (PMID 32014045, 2020). "Significantly reduced or absent GALNS enzyme activity in isolated leukocytes or cultured skin fibroblasts is diagnostic of Morquio A syndrome; however, additional enzyme analyses to rule out Morquio B syndrome and multiple sulfatase deficiency are highly recommended for definitive diagnosis." (PMID 25001525, 2014). "Mucopolysaccharidosis IVA (MPS IVA; Morquio A syndrome; OMIM #253000), is an autosomal recessive disorder caused by deficiency of N-acetylgalactosamine-6-sulfatase (GALNS)." (PMID 20808938, 2010). "Approved by the FDA and EMA for the use in children and adults with Morquio A syndrome in 2014, ERT for MPS IVA is based on treatment with recombinant human GALNS, or elosulfase alfa, for intravenous administration." (PMID 35538504, 2022). "GALNS is an enzyme responsible for MPS type IVA (MPS IVA: OMIM 253000), also known as Morquio A syndrome." (PMID 35897729, 2022). "Traditionally, treatment of Morquio A syndrome has been limited to management of symptoms and palliative care; however, enzyme replacement therapy (ERT) using recombinant human GALNS enzyme (rhGALNS) has shown great advancements and promise." (PMID 33957983, 2021).
Morquio A syndrome (continued). "Morquio A syndrome (Mucopolysaccharidosis type IVA) (MPS IVA) is a rare inherited metabolic disorder characterized by the defective degradation of keratan sulfate and chondroitin-6-sulfate, due to the abnormal or absent activity of N-acetylgalactosamine-6-sulfatase (GALNS gene)." (PMID 24348578, 2013).